MFN2 (mitofusin 2)
Diseases named in the same sentence as MFN2 in open-access papers (continued):
Sharing a sentence is not in itself a finding about the gene and the disease.
breast carcinoma (29 papers, 2015 to 2025). "Here, we report that breast cancer patients with low MFN2 expression are associated with poor prognosis as compared to patients with high MFN2 expression." (PMID 28176801, 2017). "The overexpression of endophilin A1 in breast cancer cells is associated with its phosphorylation and translocation to mitochondria; it also enhances mitochondrial fusion and the expression of both mitochondrial fusion and biogenesis-associated proteins, such as Mitofusin 2 (MFN2) and PGC-1α." (PMID 31052256, 2019). "In breast cancer cells, phosphorylated Cav-1 interacts with Mitofusin 2 (Mfn2) and Dynamin related protein 1 (Drp1), keeping them away from mitochondria, thereby reducing mitophagy." (PMID 41030451, 2025). "ERβ achieves this by promoting mitofusin 2 (MFN2) gene expression, and inducing G2 cell cycle arrest, thereby inhibiting the proliferation of breast cancer cells." (PMID 39194700, 2024). "Previous studies have shown that low expression of MFN2 is related to poor progression in hepatocellular carcinoma, lung cancer, and breast cancer, consistent with our results." (PMID 36877954, 2023). "In breast cancer, decreased expression of MFN2 was observed, accompanied by the hypermethylation of its promoter." (PMID 35887244, 2022). "Several studies have reported antitumor effects of MFN2 in different malignancies, including gastric cancers, breast cancer, hepatocellular carcinoma and urinary bladder cancer." (PMID 34956177, 2021). "By contrast, patients with breast cancer expressing low MFN2 levels show poor prognosis, at least partly due to the ability of MFN2 to inhibit mTORC2." (PMID 34482801, 2021). "ERβ knockdown results in a significant growth of several breast cancer cells, accompanied by elevated cyclin A2 expression and mitofusin 2 (mfn2)." (PMID 32944243, 2020). "Some scholars have confirmed that E2 can inhibit the proliferation of breast cancer cells by inhibiting the expression of Mfn2." (PMID 33324344, 2020). "Previous studies on Mfn2 mostly focused on pulmonary fibrosis, breast cancer, liver fibrosis, and Alzheimer’s disease, and there was little research on pelvic floor dysfunction." (PMID 33324344, 2020). "In ovarian cancer, breast cancer, and melanoma, Mfn2 knockdown suppresses oxygen consumption rate (OCR)." (PMID 31551926, 2019). "The restoration of MFN2 level with deleted 3ʹUTR sequence (pMfn2) did not decrease miR-195 induced apoptosis thereby suggesting that the pro-apoptotic role of miR-195 is MFN2-independent in breast cancer cells." (PMID 30932749, 2019). "Lower Mfn2 expression is observed in breast cancer, lung cancer, urinary bladder cancers, hepatocellular carcinoma, colorectal cancer, and gastric cancer, compared to the normal tissue." (PMID 31551926, 2019). "Further analyzing our illumina microarray data, we found a differential expression of MFN2 upon over-expression of miR-195 in breast cancer cells." (PMID 30932749, 2019). "MFN2 significantly inhibit the proliferation of breast cancer cells in vitro and increase the chemo-sensitivity of cancer cells to induce their apoptosis." (PMID 30498519, 2018). "Previous studies have shown that MFN2 plays an important anti-proliferative effect in breast cancer cells." (PMID 30498519, 2018). "Studies showed that the expression of MFN2 in colorectal cancer tissues and breast cancer tissues is significantly lower than that in normal adjacent tissues." (PMID 30498519, 2018). "By using this set of data, Patient survival curve demonstrated that breast cancer patients with low MFN2 expression indeed had a poor prognosis, confirming that decreased levels of MFN2 were associated with poor prognosis in breast cancer patients." (PMID 28176801, 2017). "We next examined the expression of fusion- and fission-related proteins (Drp1, Mfn1, and Mfn2) in breast cancer cells." (PMID 26517089, 2015). "MFN2 was shown to be a direct target of miR-195 in breast cancer cells." (PMID 35887244, 2022).
breast carcinoma (continued). "Other mechanisms could involve TRIM28, the phosphorylation of which was shown to downregulate Mfn2 in response to starvation-induced oxidative stress in breast cancer cells." (PMID 33757833, 2021). "A study on mitochondrial transplantation in breast cancer cell lines found that the protein levels of MFN2 and OPA1 in the cells significantly increased after the transplantation of exogenous healthy mitochondria into breast cancer cells, while the protein level of drp1 dramatically decreased." (PMID 33816265, 2021). "Herein, we have validated mitofusin-2 as a direct target of miR-195 in breast cancer cell lines." (PMID 30932749, 2019). "In our and others studies, Mfn2 could induce Hela cells into mitochondrial apoptosis, pancreatic cancer into cell autophagy, and breast cancer into DNA methylation, as a tumour suppressor in many cancers." (PMID 31384172, 2019). "We also identified MFN2 to be a direct target of miR-195 in apoptotic breast cancer cell lines." (PMID 30932749, 2019). "(K) Mfn2 knockdown decreases cellular proliferation in H460 (lung cancer cells), HeLa (cervical cancer cells), BT549 (breast cancer cells), and MCF7 (breast cancer cells)." (PMID 30694178, 2019). "Even though MFN1 expression levels in breast cancer also correlate with worse prognosis, our data indicate that MFN1 or MFN2 deletion does not affect breast cancer cells migration, proliferation, or adhesion." (PMID 35279198, 2022). "Our findings suggest that the pro-apoptotic effects exerted by miR-195 did not get reversed upon restoring MFN2 levels in both breast cancer cell lines." (PMID 30932749, 2019). "In human breast cancer, overexpression of Mfn2 inhibited the Ras-ERK1/2 signaling pathway, but with deletion of the p21Ras motif partially reduced the anti-tumor function of Mfn2." (PMID 31384172, 2019). "The miR-195 has been previously reported to target MFN2 in Alzheimer's disease mice but the correlation of miR-195 and MFN2 and its implication on mitochondrial dynamics has not been explored before in breast cancer." (PMID 30932749, 2019).
hepatocellular carcinoma (27 papers, 2014 to 2025). A malignant tumor that arises from hepatocytes. "Hepatic-specific knockdown of MFN2 in mice causes inflammation, triglyceride accumulation, fibrosis, and hepatocellular carcinoma; however, re-expression in a mouse model of NASH ameliorates these conditions, highlighting the beneficial role played by MFN2 in NAFLD." (PMID 38812059, 2024). "The mitochondrial GTPase mitofusin-2 (MFN2) gene encodes a mitochondrial membrane protein that can induce apoptosis of hepatocellular carcinoma (HCC) via the mitochondrial apoptotic pathway, as validated in our previous research." (PMID 27389277, 2016). "Altered expression of MFN2 has been, for example, reported in different types of tumors such as hepatocellular carcinoma, breast, lung, cervical and pancreatic cancer." (PMID 41226512, 2025). "In the current study, after treatment with sorafenib, MFN2 expression was decreased in cardiomyocytes but increased in the hepatoma cell line." (PMID 35154486, 2022). "Overexpression of Mfn2 in hepatocellular carcinoma cells leads to calcium ion (Ca2+) influx from the ER." (PMID 34026850, 2021). "Further demonstrating the tumor-suppressive role of mitofusin-2, a panel of hepatocellular carcinoma (HCC) showed significant downregulation of mitofusin-2 and correlated with worse overall survival." (PMID 28603693, 2017). "Interestingly, sor treatment increased MFN2 expression in the hepatic carcinoma cell line, Huh7, in a dose-dependent manner." (PMID 35154486, 2022). "Moreover, low levels of Mfn-2 expression correlate with a poorer prognosis in breast cancer patients and low Mfn-1 is associated with an increased metastatic capacity in hepatocellular carcinoma (HCC)." (PMID 35454774, 2022). "Glucocorticoids repress MFN2 expression in hepatoma cells and in mouse liver." (PMID 34073868, 2021). "A further study has shown that the overexpression of Mfn2 inhibits hepatocellular carcinoma cell proliferation and induces apoptosis via Bax, and adenovirus-mediated Mfn2 upregulation significantly suppresses the growth of subcutaneous tumors in nude mice both in vivo and in vitro." (PMID 25120590, 2014). "PITPNM3, one of member of a large family of G protein-coupled receptors, promotes the development of different cancer, such as in hepatic carcinoma, mitofusin-2 could interact with transcription factor SP1 to suppress PITPNM3 expression, which contributed to the inhibition of tumor." (PMID 35609322, 2022). "In hepatoma cells, highly activated mTOR signaling increases the interaction of the M2 isoform of pyruvate kinase 2 (PKM2) and Mfn2 by phosphorylating Mfn2 and thereby inhibiting the activity of PKM2 and glycolysis." (PMID 34868997, 2021). "To determine whether ASOs can be used to modulate mitochondrial dynamics, we administered a panel of ASOs targeting mitochondrial fusion and fission factors (Mfn1, Mfn2, Drp1, Fis1, Mff, Mief1, Mief2) to MHT (mouse hepatocellular carcinoma) cells in culture." (PMID 34698563, 2022). "Overexpression of Mfn2 promotes BAX translocation from the cytoplasm to the mitochondrial membrane, which induces apoptosis in many tumor cells, including hepatocellular carcinoma cells, breast carcinoma cells, urinary bladder carcinoma cells, and cervical carcinoma cells." (PMID 34026850, 2021). "Using confocal microscopy and biochemical fractionation in HuH7 hepatoma cells, authors showed localization of MAVS in MAM together with typical MAM proteins such as acyl-CoA synthetase long chain family member 4, calnexin, or Mfn2." (PMID 31540165, 2019).
Charcot-Marie-Tooth disease (26 papers, 2010 to 2025). An inherited degenerative disorder involving the peripheral nerves. "Mitofusin 2 is an essential large GTPase protein that orchestrates fusion of outer mitochondria membranes, and mutations in the encoding gene are causative for Charcot-Marie-Tooth disease." (PMID 36530473, 2022). "MFN2 mutations in humans are a common cause of Charcot-Marie-Tooth disease (type 2A), an autosomal dominant axonal neuropathy with associated muscle atrophy." (PMID 36125902, 2022). "Because MFN2 is required for axonal mitochondrial transport in neurons, dysfunction of MFN2 has been associated with several neurodegenerative diseases, such as Charcot-Marie-Tooth disease and Alzheimer’s disease." (PMID 34482801, 2021). "Gender, age at onset, initial symptoms of Charcot-Marie-Tooth disease, phenotype and point mutations in the eight unrelated Norwegian families with mutation in the MFN2 gene." (PMID 20350294, 2010). "Besides MFN2, Charcot-Marie-Tooth disease can be further caused by mutations in GDAP1." (PMID 34295920, 2021). "Mutations in MFN2 are known to be the leading cause of axonal Charcot-Marie-Tooth disease (CMT), and are found in patients with CMT type 2A and also in patients with hereditary motor and sensory neuropathy type (HMSN) type VI." (PMID 23840650, 2013). "For example, our model correctly classified all 14 pathogenic variants for Charcot-Marie-Tooth disease, despite their being spread in different genes (LMNA, MFN2 and GARS1)." (PMID 41155097, 2025). "Subsequently, we applied sABE to introduce mutations related to glycogen storage disease (T1214C in GAA) and Charcot-Marie-Tooth disease (A494G in MFN2) in HEK293T cells." (PMID 37434184, 2023). "Charcot-Marie-Tooth (CMT) disease is one of the most common genetically inherited neurological disorders and CMT type 2A (CMT 2A) is caused by dominant mutations in the mitofusin-2 (MFN2) gene." (PMID 34602978, 2021). "For example, Charcot-Marie-Tooth (CMT) diseases have been linked to 870 mutations in over 80 genes, such as PMP22, MPZ, GJB1 or MFN2." (PMID 32817118, 2020). "Mice deficient in Mfn1, Mfn2, and OPA1 are all embryonic lethal and in humans, mutations in OPA1 are linked to hereditary blindness, and Mfn2 mutations are known to cause Charcot-Marie-Tooth disease." (PMID 29062571, 2017). "MFN2, one of the core genes in the mitochondrial fusion machinery, is responsible for a very common hereditary neuropathy, Charcot-Marie-Tooth disease." (PMID 24709813, 2014). "Mitofusin-2 (Mfn2), a potential target molecule, has been extensively studied in Charcot-Marie-Tooth (CMT) disease (a heterogeneous group of inherited peripheral neuropathies)." (PMID 23797661, 2013). "Knockout mice of Mfn1, Mfn2, and OPA1 are all embryonic lethal and mutations in OPA1 in humans are associated with hereditary blindness, while Mfn2 mutations are the cause of Charcot-Marie-Tooth disease." (PMID 28097021, 2016).
sarcopenia (25 papers, 2014 to 2026). Progressive decline in muscle mass due to aging which results in decreased functional capacity of muscles. "In mouse models, a decline in MFN2 expression in skeletal muscle has been linked to age-related sarcopenia.." (PMID 41481647, 2026). "Previous study reports that mitofusin 2 deficiency links sarcopenia and impairs autophagy to activation of mitophagy." (PMID 41156549, 2025). "During aging, reduced levels of the mitochondrial fusion protein mitofusin 2 (Mfn2) are closely associated with metabolic dysregulation and sarcopenia." (PMID 40661078, 2025). "Mfn2 deficiency in aging muscle worsens age-related mitochondrial dysfunction, underlying the age-related alterations in metabolic homeostasis and sarcopenia." (PMID 39852400, 2025). "For example, age-dependent loss or genetic disruption of Mfn2 in mouse skeletal muscle causes sarcopenia via inhibition of mitophagy." (PMID 36312227, 2022). "In our previous work, we showed that during aging there is a reduction of Mfn2 protein in mouse muscle, which leads to inhibition of mitophagy and is associated with age‐induced metabolic disease and sarcopenia." (PMID 35263007, 2022). "In the context of sarcopenia, MFN2 has been shown to play a key role in mitigating muscle loss." (PMID 40565245, 2025). "In particular, deletion of Mfn2 in young animals causes muscle atrophy due to extensive mitochondrial fragmentation, ROS production, endoplasmic reticulum stress, inhibition of autophagy, and exacerbation of sarcopenia." (PMID 36561214, 2022). "Moreover, a recent study by Sebastián and colleagues demonstrated that mfn2 deficiency in the skeletal muscle enhances age-induced mitochondrial dysfunction and promoted sarcopenia." (PMID 30988232, 2019). "However, the loss of the fusion-promoting factor Mfn2 (Mitofusin-2) in skeletal muscles causes symptoms reminiscent of sarcopenia, at least in mouse." (PMID 24642473, 2014). "In addition, the loss of MFN2 protein expression in skeletal muscles correlates with age and could contribute to sarcopenia through a similar inflammatory mechanism." (PMID 40175090, 2025). "Given that high circulatory levels of mtDNA are associated with sarcopenia, this finding offers another potential mechanism through which exercise‐mediated restoration of MFN2 protects against sarcopenia, but further investigation into how mtDNA content may alter mitochondrial structure is valuable." (PMID 40285369, 2025). "Interestingly, genetic loss of function of Mfn2 and Opa1 in mice is sufficient to cause sarcopenia, suggesting that the down regulation we observed in sarcopenia could be causal in the loss of muscle mass and strength." (PMID 31862890, 2019). "Dysregulation of MFN2 can lead to neurodegeneration, sarcopenia, metabolic disease, heart disease and many other diseases." (PMID 36968589, 2023). "The downregulation of Mfn2 and Opa1 expression in sarcopenia muscle suggests that mitochondrial fusion participate in the pathogenesis of sarcopenia." (PMID 37196123, 2023). "In line, MFN2, OPA1, or DRP1 deficiency negatively affect muscle health and mitochondrial homeostasis, triggering the insurgence of sarcopenia features, such as muscle atrophy." (PMID 35276842, 2022). "Expression levels of Mfn2, Fis1, Drp1, and Opa1 in sarcopenic muscle are down-regulated, suggesting a role for mitochondrial dysfunction in the pathogenesis of sarcopenia and skeletal muscle atrophy." (PMID 36561214, 2022). "Other studies have shown that the progression of sarcopenia involves impaired mitochondrial quality, which is marked by the reduction or loss of OPA1, MFN2, and DRP1 expression." (PMID 35432979, 2022). "In another study, the expression levels of Mfn2, Fis1 and Opa1 were downregulated in sarcopenic muscle, suggesting that mitochondrial dynamics participates in the pathogenesis of sarcopenia." (PMID 34881083, 2021).
sarcopenia (continued). "The use of an in vitro cell exercise model showed that the mechanism by which exercise counteracts the effects of sarcopenia, age‐related disease may be due to increased expression of MFN‐2 during exercise." (PMID 40285369, 2025). "We sought to extend these findings to determine whether MFN2 further plays a critical role in mitochondrial structure remodeling in exercise to protect against sarcopenia." (PMID 40285369, 2025). "Moreover, during aging—which is generally characterized by sarcopenia—MFN2 levels are typically reduced." (PMID 40565245, 2025). "The gene mfn2 controls muscle mitochondrial damage, and its age-related decrease in muscles is a determinant of the inhibition of mitophagy and accumulation of damaged mitochondria, triggering the induction of muscle atrophy and even sarcopenia." (PMID 37109470, 2023). "Mfn2 protein expression was also markedly decreased in hip-fractured patients with sarcopenia." (PMID 34881083, 2021). "Furthermore, independent from exercise, it is unclear whether MFN2 can be delivered to recapitulate the therapeutic effects of exercise on sarcopenia." (PMID 40285369, 2025). "Intriguingly, fusion-related proteins (Mfn1/Mfn2) were significantly upregulated in older wild type (WT) mice due to the downregulation of fission protein Fis1, which is consistent with the results obtained in some hip-fractured patients of advanced age with sarcopenia." (PMID 34881083, 2021). "The higher expression of Mfn2 and OPA1 observed in the soleus is particularly interesting because two recent studies showed that Mfn2 and OPA1 deficiencies are strongly involved in sarcopenia, aging-associated oxidative stress and unfolded protein response activation." (PMID 30449736, 2018). "MFN2 and OPA1 levels decreased from months 6 to 10, indicating reduced mitochondrial fusion during the progression of sarcopenia." (PMID 39971301, 2025). "In addition, suppression of Mfn2 and OPA1 in skeletal muscles of elderly mice exacerbates metabolic changes and sarcopenia due to impaired mitochondrial quality and autophagy." (PMID 36561214, 2022). "Similarly, mitochondrial fusion genes (Mfn2 and Opa1) were substantially downregulated in old SAMP8 mice and demonstrated a downward trend during the whole progression of sarcopenia." (PMID 34881083, 2021). "Whether enhancing/overexpressing mitochondrial fusion proteins, such as Mfn2 in muscles of aged WT mice, can attenuate the progression of sarcopenia has never been tested." (PMID 34360946, 2021).